EGFR (epidermal growth factor receptor)
Diseases named in the same sentence as EGFR in open-access papers (continued):
Sharing a sentence is not in itself a finding about the gene and the disease.
prostate carcinoma (continued). "However, PC-3 cells was more sensitive to treatment with EGFR inhibitor AG1478, suggesting a possibility of using AG1478 as treatment for prostate cancer bone metastasis." (PMID 24349321, 2013). "Unlike locally-advanced prostate cancer, strong EGFR expression was observed in one quarter of the studied patients, as reported by other investigators in early stage prostate cancer." (PMID 22546016, 2012). "Recent studies showed that EGFR (epidermal growth factor receptor) protein expression and EGF-induced phosphorylation of Erk1/2 (extra cellular signal regulated kinases) were found to be downregulated by prostasin expression in PC-3 prostate cancer cells." (PMID 23319948, 2012). "In prostate cancer cells, neurotensin also stimulated ERK phosphorylation in a PKC-dependent manner, but in these cells activation of PKC mediated transactivation of the EGFR." (PMID 21961726, 2011). "In the present study, the combined impact of the mammalian target of rapamycin (mTOR)-inhibitor RAD001, the dual EGFr and VGEFr tyrosine kinase inhibitor AEE788 and the histone deacetylase (HDAC)-inhibitor valproic acid (VPA) on prostate cancer growth and adhesion in vitro was investigated." (PMID 21867506, 2011). "Besides the CDKN/pRb pathways, Id1/3-PA7 could interestingly be used to analyse EGFR pathway-dependent functions, as Id proteins, especially Id1, induce upregulation of EGFR in different tumour cells, very frequently in androgen-independent prostate cancer cells." (PMID 20842131, 2010). "In this study, we attempted to extend these observations to confirm whether EGFR and Her-2 are involved in the constitutive activation of PI3K/Akt and NF-κB signalling pathways in prostate cancer tissues." (PMID 20216540, 2010). "More recently, it was shown that NTSR1 activation results in EGFR transactivation by the shedding of transforming growth factor-α (TGF-α) in pancreas, and HB-EGF or amphiregulin in prostate cancer cells, both leading to ERK1/2 activation, but also EGFR expression." (PMID 19156213, 2009). "While transcriptional targets of EGFR were enriched in AI prostate cancer, EGFR mRNA itself did not appear elevated in AI cell lines." (PMID 17598908, 2007). "If more prostate cancer cell lines were profiled, it might uncover additional subtypes of AI PCA to the EGFR-dependent subtype uncovered here." (PMID 17598908, 2007). "An extensive in-silico investigation into rutin compounds as potential inhibitors of prostate cancer signaling pathways revealed that the AKT, EGFR, and ERK signaling pathways were targeted by rutin derivatives, which could prevent prostate cancer from spreading." (PMID 41142938, 2025). "Bidirectional crosstalk between AR and epidermal growth factor receptor (EGFR) pathways further implicates therapeutic synergy, suggesting that androgen deprivation therapy (ADT), established in prostate cancer, may offer utility in AR+ TNBC either concurrently or sequentially." (PMID 41383624, 2025). "Moreover, GREM1 has been described to bind and signal to vascular endothelial growth factor receptor (VEGFR) and stimulate angiogenesis, as well as epidermal and fibroblast growth factor receptor (EGFR and FGFR) to elicit tumor-promoting effects in breast and prostate cancer, respectively." (PMID 37615860, 2023). "In this respect, a pharmacophore directed against the epidermal growth factor receptor (EGFR) may be a promising hybridization partner, as the EGFR is also overexpressed and/or overactive in various solid tumors, including hepatocellular and prostate cancer." (PMID 34445133, 2021). "The “prostate cancer” pathway also comprises genes that are relatively specific to the (human) prostate (CREB3L4, KLK2, NKX3-1 and SRD5A2), proto-oncogenes (EGFR, NRAS, PDGFRA and PDGFRB), and druggable candidates (CDKN1A, CTNNB1, EGFR, NRAS, PDGFRA, PDGFRB, PIK3CD and PIK3CG)." (PMID 34768937, 2021).
prostate carcinoma (continued). "Interestingly, TRIM24 could function as transcriptional regulator of both PIK3CA and EGFR genes in prostate cancer, and that PIK3CA and EGFR had synergetic roles in activation of the PI3K/AKT pathway in prostate cancer and other types of tumors." (PMID 33643926, 2021). "After identifying EGFR as the target of exosomal miR‐3934‐5p and clarifying the regulating role of EWI‐2 on the sorting and enrichment of miR‐3934‐5p into the exosomes, we then analyzed the functional roles of EWI‐2 in the regulation of prostate cancer cell signal transduction." (PMID 33605506, 2021). "This gives us new clues about the role of PTRF restoration in PC3 cells that do not have a functional effect on the inhibition of prostate cancer metastasis or may be balanced by the EGFR activation." (PMID 33605506, 2021). "EGFR is overexpressed in prostate cancer, in 31–48% of bladder cancer and 25–77% of colon and rectal cancer as well, which might reduce the specificity for the detection of PSCC by using imaging modalities with antibodies directed against EGFR." (PMID 32942549, 2020). "Additionally, it was revealed that in breast and prostate cancers ACKR3 may form heterodimers of another type, with epidermal growth factor receptor (EGFR), what contributes to promoting tumor cell proliferation in these malignancies." (PMID 32456359, 2020). "In order to understand whether androgen resistance or independence might be driving EGFR expression, we performed qRT-PCR and Western blot analysis using five different prostate cancer cell lines (LNCaP, C4-2, DU145, PC3, and LNCaP-FUT8) to evaluate EGFR expression." (PMID 32085441, 2020). "To assess whether other molecules in the prostate cancer cell were affected by the expression of SCIN, we preliminarily used a gene expression chip to screen PC‐3 cells (unpublished data) and found that the EGFR and RPS6KA2 expression was regulated by SCIN." (PMID 29744289, 2018). "Since EGFR-based therapeutics showed no beneficial effects in prostate cancer, it is important to determine whether the ETV6-TWIST1 axis plays a role in the development of drug resistance." (PMID 29455655, 2018). "Using the prostate cancer LNCaP cell line, which is also endowed with AR-T877A mutated variant, we observe that 50 and 100 μM BPA causes cell cycle arrest which is mediated by a non-transcriptional mechanism involving EGFR, ERK, AR, and ERβ." (PMID 29383186, 2017). "In addition, Mag inhibits EGFR, PI3K, and Akt activation in human prostate cancer." (PMID 27074557, 2016). "However, in the present study, we demonstrated that, unlike p120ctn, overexpression of δ-catenin enhanced EGFR signaling in CWR22Rv-1 prostate cancer cells." (PMID 26883159, 2016). "However, there is no convincing evidence so far that P2Y2 receptor promotes prostate cancer progression via EGFR." (PMID 26182292, 2015). "miR-143 could increase the drug-sensitivity of prostate cancer by suppressing the expression of target protein KRAS, while the overexpression of miR-143 could also participate the regulation of EGFR/RAS/MAPK pathway and improve the sensitivity of prostate cancer cells to docetaxel." (PMID 25342041, 2014). "Here we report that treatment of prostate cancer cells with M-110 or a structurally unrelated PIM kinase inhibitor SGI-1776 increases the expression of MIG6 RNA and protein and inhibits EGF induced activation of the EGFR and the downstream ERK MAPkinase pathway." (PMID 22193779, 2011). "Additionally, miR-146a promotes NF-kB signaling in oral, cervical, breast, and prostate cancers through the targeting of IRAK1 and TRAF6, and it enhances cell growth and proliferative signaling in several cancers—including breast, liver, lung, prostate, and gastric—by targeting EGFR." (PMID 40277937, 2025).
prostate carcinoma (continued). "Similarly, other members of the Erb family that are capable of forming heterodimers with EGFR or posttranslational modifications and overexpression of other cell surface receptors, including IGF-1, identified in our proteomics data have been shown to play anti-apoptotic roles in prostate cancer." (PMID 32085441, 2020). "In human prostate cancers, tuft-like cells express COX1, active EGFR and active SFKs, but not DCLK1 and COX2." (PMID 37386128, 2023). "When comparing three widely studied prostate cancer cell lines, we observed a negative correlation between DHRS7 and EGFR expression." (PMID 35804847, 2022). "To test the effects of Rosuvastatin treatment on the outcome of prostate cancer, we monitored the levels of PSA, CAV1 and EGFR at baseline, after 3 and 6 months in statin and non-statin users PC patients." (PMID 36480560, 2022). "While the overall survival of EGFR and CXCL14 expression and the Gleason score of prostate cancer patients is without significant difference." (PMID 34696665, 2021). "Prolactin receptor (PRLR), which has been suggested as a therapeutic target in subgroups of breast and of prostate cancer, was overexpressed in EGFR-positive tumors compared to ALK/EGFR-negative tumors and compared to ALK-positive tumors (FC = 3.8, p = 0.0004 and FC = 2.6, p = 0.013)." (PMID 34125345, 2022). "However, in our analysis, no gene amplification of the EGFR, the HER2, or the c-Met has been observed in cetuximab treated DU﻿﻿﻿﻿145 prostate carcinoma cells." (PMID 34321039, 2021). "Consistently in prostate cancer cells perifosine was able to determine a reduction of AKT activity, cell proliferation, and to induce apoptosis after stimulation with 50 ng/ml EGF, although no data concerning EGFR activation were shown so far." (PMID 22590625, 2012). "However, other study reported no alteration of EGFR signaling in response to KAI1 expression in DU145 and PC3 prostate cancer cell lines." (PMID 22390300, 2012). "Thus, while neurotensin did not induce transactivation of the EGFR in Panc-1 cells, PKC-dependent transactivation of the EGFR mediated the mitogenic effect of neurotensin on prostate cancer cells." (PMID 21961726, 2011).
ovarian carcinoma (755 papers, 1991 to 2026). A malignant neoplasm originating from the surface ovarian epithelium. "In ovarian cancer, EGFR overexpression is associated with poor prognosis and decreased responsiveness to chemotherapy." (PMID 39858026, 2025). "Upregulated EGFR expression is associated with poor prognosis in cancers and has been highly expressed in ovarian cancer, triggering poor prognosis." (PMID 40172364, 2025). "As a consequence, the overexpression of EGFR has been linked to numerous cancers, including head, neck, lung, breast, colon, kidney, prostate, pancreas, brain, and ovarian cancer." (PMID 38254833, 2024). "EGFR, as a target in the spread of ovarian cancer through the intraperitoneal cavity, causes severe morbidity and lethality." (PMID 38496894, 2024). "PAR2 was shown to be significantly overexpressed in clinical tissues of ovarian cancer via association with β-arrestin and cross-talk with epidermal growth factor receptor (EGFR)." (PMID 38275417, 2024). "Parallelly, the Epidermal Growth Factor Receptor (EGFR) is frequently overexpressed in ovarian cancer and is associated with poor prognosis." (PMID 37964873, 2023). "The overexpression of EGFR and/or ErbB2 frequently occur in human ovarian cancer; this is associated with more aggressive tumor behavior and poorer patient outcomes." (PMID 36770705, 2023). "And our previous study revealed that monensin can inhibit multiple cancer-associated signaling pathways, including EGFR-signaling, in human ovarian cancer cells." (PMID 36896461, 2023). "The stimulatory effects of fentanyl in ovarian cancer cells are attributed to its ability in activating EGFR, and this is associated with μ opioid-receptor." (PMID 35999506, 2022). "In this work, we demonstrate that fentanyl enhances ovarian cancer cell biological functions and reverses chemotherapy-induced apoptosis through activation of EGFR, and furthermore that this is associated with opioid receptor." (PMID 35999506, 2022). "For example, EGFR was associated with the mTOR pathway to mediate ferroptosis and apoptosis of ovarian cancer." (PMID 35359830, 2022). "Although the EGFR signaling pathway is usually activated and associated with a poor prognosis, clinical results of EGFR inhibition in recurrent ovarian cancer patients are disappointing." (PMID 36275669, 2022). "In ovarian cancer, high EGFR expression is often associated with a more aggressive, invasive, and metastatic disease." (PMID 34503128, 2021). "Transfection of FUT1 into ovarian cancer cells RMG-I to increase the expression of Lewisy caused enhanced phosphorylation of EGFR." (PMID 34069424, 2021). "Transwell migration assays revealed that EGFR-IL-6-STAT3 pathway activation was linked to increased ovarian cancer cell migration." (PMID 34369236, 2021). "Aside from EGFR, fibroblast growth factor receptors (FGFRs) have also been implicated in ovarian cancer malignancy." (PMID 34577144, 2021). "The EGFR/ERK signaling pathway is upregulated in many cancer types including ovarian cancer and is frequently implicated in treatment resistance." (PMID 32231055, 2020). "In previous reports, EGFR gene amplification was associated with poor patient outcome in ovarian cancer and was detected in 4–22% of cases." (PMID 33207545, 2020). "The downregulation of EGFR caused by calcitriol leads to a decreased response of ovarian cancer cells to the epidermal growth factor." (PMID 32024052, 2020). "The association of HE4 overexpression with epithelial ovarian cancer progression has been related to its effects on the EGFR-MAPK signaling pathway and ECM-receptor interaction pathway." (PMID 33134179, 2020). "A previous study has revealed that cisplatin-resistant human ovarian cancer cell lines have an enhanced rate of motility and invasion in vitro, which is associated with hyperactivation of EGFR." (PMID 32660222, 2020).
ovarian carcinoma (continued). "Three networks (Network #1, #5, and #12) were linked to EGFR/ERBB2 signaling pathways that are well-known to have a major role in ovarian cancer." (PMID 33228226, 2020). "In this regard, a proof-of-concept synthetic peptide that can cause degradation of EGFR has been shown to be effective in treating orthotopic ovarian cancers in mice by inducing mitophagic cell death of cancer cells." (PMID 31508364, 2019). "Because EGFR is overexpressed in up to 70% of ovarian cancers and is associated with poor prognosis, monoclonal anti-EGFR antibodies such as cetuximab have been added to paclitaxel and platinum-based agents in patients with recurrent ovarian cancer." (PMID 31355133, 2019). "Our data demonstrated that the sensitization of anti-EGFR-sensitive ovarian cancer cells with anti-EGFR TKIs caused increasing functional resistance." (PMID 31546690, 2019). "For our studies, we selected the constitutively anti-EGFR-susceptible ovarian cancer cell line IGROV-1 and SKOV-3 with intrinsic resistance to cetuximab." (PMID 31546690, 2019). "The EGFR signaling pathway is known to be overexpressed and associated with poor prognosis in more than 70% of ovarian cancer patients." (PMID 30375371, 2018). "EGFR is widely expressed in 33–75% of ovarian cancer and has been implicated in the growth and progression of this cancer; therefore, EGFR is important to represent a potential target for anticancer drug development." (PMID 29891015, 2018). "Our results suggest that GALNT6 expression is associated with poor prognosis of ovarian cancer and enhances the aggressive behavior of ovarian cancer cells by regulating EGFR activity." (PMID 28388560, 2017). "EGFR is overexpressed in most of ovarian carcinomas compared to normal tissues and has been associated with poor prognosis." (PMID 28446239, 2017). "Epidermal growth factor receptor signaling caused ovarian cancer cells to resist cisplatin and to recur because of the EMT process." (PMID 28231820, 2017). "EGFR is commonly present in 33% to 75% of ovarian cancers and increased EGFR is associated with poor survival in ovarian cancer patients." (PMID 29383145, 2017). "EGFR amplification, mutations and overexpression have been extensively and variably reported in ovarian carcinoma." (PMID 26870997, 2016). "EGFR is reported to be both increased in copy number and overexpressed in serious ovarian carcinoma and is associated with a high tumour grade, large residual tumour size, high proliferation index and poor patient outcome." (PMID 28936249, 2016). "Many studies have demonstrated that epidermal growth factor receptor (EGFR) is overexpressed in human ovarian cancer, and EGFR overexpression is associated with more aggressive clinical behavior and a poor prognosis." (PMID 27835572, 2016). "Here we investigated the mechanisms underlying the resistance to EGFR inhibition in ovarian cancer and developed a strategy to overcome it." (PMID 25928246, 2015). "Taken together, these results provide a molecular mechanism underlying resistance to EGFR inhibition in human ovarian cancer." (PMID 25928246, 2015). "The EGF-receptor is over-expressed in 70% of ovarian cancers and associated with poor prognosis, suggesting that EGFR is an attractive therapeutic target in this cancer." (PMID 25928246, 2015). "The absence or weak staining of BRAF (Negative and weak staining in tumor cell cytoplasm was considered to be mutation BRAF) (P = 0.045) and high EGFR expression (P = 0.041) were associated with the ovarian cancer histotype." (PMID 26490766, 2015). "The EGFR signaling pathway is frequently activated in human ovarian cancer and associated with poor prognosis." (PMID 25928246, 2015). "EGFR has been found in 33–75% of ovarian cancers and has been implicated for growth and progression of ovarian cancer." (PMID 25180175, 2014).